RN7SKP147 (RN7SK pseudogene 147)
Gene: Miscellaneous RNA gene on chromosome 21 (20,356,653 to 20,356,896, forward strand). Ensembl gene ENSG00000252963.
Homologues: Orthologues: chimpanzee 7SK (95% identical), mouse Gm54881 (48% identical), guinea pig 7SK (45% identical), mouse Gm55389 (41% identical). Paralogues in human: RN7SKP294 (64% identical), 7SK (64% identical), RN7SKP249 (63% identical), RN7SKP176 (63% identical), RN7SKP203 (63% identical), RN7SKP20 (62% identical), RN7SKP227 (62% identical), RN7SKP281 (62% identical), RN7SKP48 (62% identical), RN7SKP103 (62% identical), RN7SKP162 (62% identical), RN7SKP170 (62% identical), and 284 more.